APLN (apelin)
Diseases named in the same sentence as APLN in open-access papers (continued):
Sharing a sentence is not in itself a finding about the gene and the disease.
liver fibrosis (continued). "This review focuses on recent advances in elucidating the roles of the endocannabinoid and apelin systems in liver fibrosis and their potential clinical relevance." (PMID 31653030, 2019). "Intriguingly, apelin displays conflicting roles in these different tissues, protecting against renal, myocardial, and pulmonary fibrosis, while potentially promoting liver fibrosis." (PMID 31492821, 2019). "Two of these signalling pathways, which have significant impact on the pathophysiology of liver fibrosis, are the endocannabinoid and apelin systems." (PMID 31653030, 2019). "In the present study, we aimed to investigate the function and mechanism of apelin in promoting hepatic fibrosis in LX-2 cells and the mice fed high-fat chow (HFC)." (PMID 31270645, 2019). "The hepatic endocannabinoid and apelin systems are two signalling pathways with a substantial role in the liver fibrosis pathophysiology—both are upregulated in patients with advanced liver disease." (PMID 31653030, 2019). "The present study demonstrated that the expression of apelin/APJ was increased in the mice fed HFC, and apelin-13 promoted hepatic fibrosis by ERK signaling in LX-2 cells." (PMID 31270645, 2019). "The EC and apelin systems are two of the multiple cell-signalling pathways involved in the pathogenesis of liver fibrosis." (PMID 31653030, 2019). "In this article, we review the role of apelin/APJ system in liver fibrosis, hepatitis, hepatic cirrhosis, liver injury and metabolic liver disease." (PMID 29340118, 2017). "Apelin is a regulatory peptide involved in various biological processes, including cardiovascular and fluid homeostasis, inflammation, cell proliferation, angiogenesis, and hepatic fibrosis." (PMID 36785790, 2023). "Furthermore, the inhibition of apelin signalling has been shown to reduce the intensity and burden of liver fibrosis in murine models." (PMID 34648138, 2021). "•Decreased circulating apelin may be a biomarker of liver fibrosis that occurs in early-stage liver disease." (PMID 33171278, 2021). "In vitro, apelin has also demonstrated a significant potential to promote liver fibrosis." (PMID 31653030, 2019). "Therefore, this study extended the knowledge in the field regarding the role of apelin in the development of liver fibrosis." (PMID 31270645, 2019). "Further studies are required to clarify the role of apelin in liver fibrosis." (PMID 31492821, 2019). "A contemporary clinical investigation revealed that circulating apelin levels are associated with histological and hemodynamic features of chronic liver disease, but more clinical studies are needed to confirm the major relevance of apelin system in human liver fibrosis." (PMID 31653030, 2019). "Overall, apelin is beneficial in a number of different disease models of tissue fibrosis in kidney, heart, and lung tissues; however, it may accentuate liver fibrosis." (PMID 31492821, 2019). "However, the biological function of apelin in liver diseases, especially liver fibrosis is still under investigation." (PMID 31270645, 2019). "One study suggested that apelin may play a different role in liver fibrosis by being an initiator of hepatic injury instead of merely a HSC activator following exogenous injury." (PMID 31653030, 2019). "The endocannabinoid and apelin systems are two of the multiple cell-signalling pathways involved in the transformation of quiescent hepatic stellate cells into myofibroblast like cells, the main matrix-producing cells in liver fibrosis." (PMID 31653030, 2019). "The authors demonstrated that apelin expression level accurately reflects the severity of hepatic fibrosis and proposed that it could be used as a prognostic factor in biliary atresia patients, to estimate the timing of liver transplantation." (PMID 29535774, 2018). "The expression level of apelin indicates the degree of hepatic fibrosis and esophageal varices, so it could be potentially considered as a prognostic factor for BA patients." (PMID 29340118, 2017).
liver fibrosis (continued). "The function of apelin/APJ in liver fibrosis still needs to be investigated." (PMID 28484393, 2017). "However, it is not known whether reductions in BMP9 and/or BMP10, with associated reduction in BMPR-II signalling, correlate with altered levels of apelin in patients with liver fibrosis and cirrhosis." (PMID 33171278, 2021). "Interestingly, apelin was highly expressed under hypoxic or proinflammatory conditions in HSCs, and it might promote liver fibrosis or cirrhosis progression." (PMID 31270645, 2019). "Apelin and APLNR can also be expressed in hepatic stellate cells and macrophages, affecting liver fibrosis in MASLD." (PMID 39744169, 2025). "This study investigated the role of microRNA-125b in PSC-related liver fibrosis, focusing on its interaction with transforming growth factor beta (TGF-β), androgen receptors (ARs), and apelin." (PMID 40869103, 2025). "Apelin is a hepatic pro-fibrotic agent, in part by mediating some of the fibrogenic effects triggered by AII and ET-1 in the activation of HSC occurring in liver fibrosis." (PMID 31653030, 2019). "However, whether the apelin could promote liver fibrosis by ERK signaling pathway remains elusive." (PMID 31270645, 2019). "Apelin/APJ gene expression is temporally increased during liver cirrhotic development and is decreased in stabilized liver fibrosis." (PMID 31653030, 2019). "In the current work, we have reveiwed the latest research progress about the role of apelin/APJ system in liver disease, including liver fibrosis, hepatitis, hepatic cirrhosis, liver injury, metabolic liver disease and fatty liver disease." (PMID 29340118, 2017). "Furthermore, there was a positive correlation between the apelin level and INR (the index to assess liver fibrosis) in the males with PSC." (PMID 40869103, 2025). "Unlike in kidney, myocardial, and lung fibrosis where apelin is beneficial, in hepatic fibrosis the role of apelin is less clear." (PMID 31492821, 2019). "In addition, apelin/APJ gene expression is temporally increased during liver cirrhotic development and it decreased in stabilized liver fibrosis formation." (PMID 28484393, 2017). "Of interest, both apelin and APJ are widely expressed throughout the lung, heart, liver, gut, kidney and central nervous system, spatially overlapping expression of the endocannabinoid system while interaction between the endocannabinoid system and apelin limits liver fibrosis." (PMID 33058425, 2020). "Therefore, apelin may, in theory, induce HSC to a pro-fibrogenic profile and prolong its stimulation autocrinally during all stages of liver fibrosis in chronic liver disease." (PMID 31653030, 2019). "Considering the close relationship between apelin expression and profibrogenic factors in HSCs, and the alleviation of fibrogenesis and angiogenesis under the condition of APJ blockade in hepatic fibrosis, the apelin/APJ system might be a promising therapeutic target for liver fibrosis." (PMID 29340118, 2017). "However, administration for 4 weeks of Fc-apelin-13 (apelin-13 fused with IgG Fc fragment) in obese mice significantly improves glucose tolerance, stroke volume, and cardiac output, while it decreases cardiac and hepatic fibrosis; but it does not affect food intake and body weight." (PMID 35355561, 2022).
ovarian carcinoma (18 papers, 2018 to 2025). A malignant neoplasm originating from the surface ovarian epithelium. "In patients with ovarian cancer treated with bevacizumab, increased expression of apelin was associated with significantly decreased disease-free survival." (PMID 32002127, 2020). "A body of evidence suggests that there is a significant association between the role of apelin and peroxisome proliferator-activated receptor gamma (PPAR) in ovarian cancer pathogenesis." (PMID 40076482, 2025). "Analyzing research on the role of apelin in ovarian cancer cells, it can be concluded that apelin exerts an impact on cancer cell migration and acts as a mitogenic factor." (PMID 40076482, 2025). "It has been demonstrated that ovarian cancer tumor development and metastasis are facilitated by elevated apelin expression in ovarian tumor cells." (PMID 40612675, 2025). "Recent reports on the effect of apelin on PARP expression also show that apelin is an interesting target for research on the effectiveness of PARP inhibition in the treatment of ovarian cancer." (PMID 40076482, 2025). "It was observed that bisphenol A-induced apelin expression in ovarian cancer cell lines activates cell proliferation via peroxisome proliferator-activated receptor gamma." (PMID 40076482, 2025). "The results of this study suggest that BPA and its derivatives induce ovarian cancer cell progression by up-regulating apelin, which acts as a mitogenic factor in these cells." (PMID 37238197, 2023). "Apelin is linked to frequent female reproductive pathological conditions such as PCOS, ovarian cancer, and endometriosis." (PMID 37424869, 2023). "Low concentrations of BPA increased apelin expression and secretion in the epithelial ovarian cancer cell line OVCAR-3." (PMID 37238197, 2023). "According to the study, the involvement of apelin in the processes of ovarian cancer development results in a shorter overall survival of patients by 14.7 months." (PMID 37190027, 2023). "Adipocyte-derived factors can increase lipid uptake in ovarian cancer cells via the apelin–APJ signaling and promote fatty acid oxidation via the AMPK-CPT1." (PMID 35565396, 2022). "Further, recent RNA seq analysis of anti-VEGF resistant ovarian cancer model showed upregulation of apelin/APJ receptor signaling pathway." (PMID 33803224, 2021). "Previous studies demonstrated that the level of APLN expression was significantly increased in ovarian cancer cells." (PMID 33240613, 2020). "It will also describe apelin linked with reproduction dysfunctions like infertility, polycystic ovarian syndrome (PCOS), endometriosis, and ovarian cancer." (PMID 29977292, 2018). "The article summarizes also results of a series of recent studies on the effect of apelin on reproduction pathology, like polycystic ovarian syndrome, endometriosis, and ovarian cancer." (PMID 29977292, 2018). "Apelin accelerated cell invasion and mobilization of ovarian cancer cells in in vitro studies." (PMID 40076482, 2025). "However, recent studies have also acknowledged that apelin exerts an anti-cancer effect on ovarian cancer cell lines." (PMID 40076482, 2025). "Furthermore, apelin is associated with reproductive disorders such as polycystic ovary syndrome (PCOS), endometriosis, and ovarian cancer." (PMID 37424869, 2023). "Recent studies also demonstrated a relationship between apelin and ovarian cancer." (PMID 37424869, 2023). "OVCAR-4 ovarian cancer cells treated with apelin showed enhanced growth and development." (PMID 37190027, 2023). "In ovarian cancer, APJ expression levels were higher in epithelial cancer cells than in granulosa tumor cells and apelin could act as a mitogenic factor in ovarian cancer cell line OVCAR-3 cell, promoting its proliferation and growth." (PMID 33912466, 2021). "Apelin was involved in mitosis in ovarian epithelial cancer cells." (PMID 30984306, 2019). "Recent data indicate the relationship between apelin and ovarian cancer." (PMID 29977292, 2018).
ovarian carcinoma (continued). "Furthermore, apelin-13 exhibited endocrine and autocrine actions in epithelial ovarian cancer." (PMID 29875677, 2018). "This apelin/APJ system enhanced migration in different types of cancer cells, including lung adenocarcinoma, ovarian cancer, gastric cancer, and oral squamous cell carcinoma." (PMID 40304310, 2025). "Apelin plays an important role in the pathogenesis of gynecological diseases, mainly in PCOS, endometriosis and ovarian cancer." (PMID 37190027, 2023). "The result was in line with the previous reports that APLN/APLNR gene expression were increased in gastric cancer, liver cancer, cholangiocarcinoma, lung cancer, ovarian cancer, prostate cancer, etc., compared with the equivalent normal tissues or cells." (PMID 36193059, 2022). "APLN/APLNR mRNA and protein expression in ovarian epithelial cancer and/or granulosa tumor cell lines were significantly higher than those of noncancer ovarian cell lines." (PMID 36193059, 2022). "Apelin is involved in cancer cell proliferation in various cancers, including NSCLC, GC, oral squamous cell carcinoma, cholangiocarcinoma, PCa and ovarian cancer." (PMID 33912466, 2021). "Summary of studies about the expressional changes of APLN and APELA in the polycystic ovary syndrome (PCOS), Ovarian cancer (OvCa), preeclampsia (PE) and gestational diabetes mellitus (GDM)." (PMID 33240613, 2020). "Recent research revealed enhanced expression of apelin, assessed by immunohistochemistry (IHC) methods, in obese ovarian cancer patients compared to non-obese individuals." (PMID 40076482, 2025). "Omental adipocytes co-cultured with ovarian cancer cells showed that apelin secreted from omental adipocytes activates the apelin/APL receptor (APJ) pathway, and further promotes ovarian cancer metastasis through the upregulation of CD36 by the APJ-STAT3 signaling pathway." (PMID 39125923, 2024). "Apelin is an adipokine, and its receptor APJ is upregulated in several ovarian cancer cell lines." (PMID 35565396, 2022). "To assess the role of increased apelin and/or APJ expression in response of ovarian cancer patients to anti-angiogenic therapy, we evaluated the differences in disease-free survival (DFS) in patients treated with bevacizumab, who expressed variable levels of the genes." (PMID 32002127, 2020). "Based on available data, we speculated that apelin has a connection with such dysfunctions like PCOS, endometriosis, and mitogenic action in ovarian cancer." (PMID 29977292, 2018). "Additionally, these data indicate that apelin stimulated OVCAR-3 cell proliferation and suggest its mitogenic action in ovarian epithelial cancer cells." (PMID 29977292, 2018). "It is also possible, that apelin induces migration via MAPK/ERK in oral cancer cells, AMPK, PI3K/Akt, and peroxisome proliferator-activated receptor (PPAR) pathways in ovarian cancer cells." (PMID 29875677, 2018). "Various apelin peptides can stimulate tumor growth and proliferation of many types of cancer cells, including cholangiocarcinoma (CAA), non-small cell lung cancer (NSCLC), gastric cancer, prostate cancer, ovarian cancer, and oral squamous cell carcinoma." (PMID 29875677, 2018). "Apelin suppresses the proliferative effect of estrogen on epithelial (OVCAR-3) ovarian cancer cell lines and insulin-like growth factor 1 (IGF-1) on granulocyte (COV434) ovarian cancer cell lines by the interaction of the apelin receptor with those hormones’ receptors." (PMID 40076482, 2025). "In support of our findings, several ovarian cancer cell lines such as OVCAR-3, -4, -5 and SKOV3 and high grade serous ovarian carcinoma (HGSOC) tissue were found to have greater expression of mRNA and protein of APLNR and its ligand apelin as compared to normal ovarian surface epithelium." (PMID 35052372, 2021). "However, the exact mechanism induced by apelin is not related to the direct activation of proteins involved in apoptosis of epithelial (OVCAR-3) and granulosa (COV434) ovarian cancer cell lines." (PMID 40076482, 2025).
atrial fibrillation (17 papers, 2015 to 2025). A disorder characterized by an electrocardiographic finding of a supraventricular arrhythmia characterized by the replacement of consistent P waves by rapid oscillations or fibrillatory waves that vary in size, shape and timing and are accompanied by an irregular ventricular response. "An analysis that included data from 34 studies involving 31,479 patients showed that adipokines, mainly adiponectin, apelin, and resistin, are associated with the risk of developing atrial fibrillation." (PMID 40725736, 2025). "There are data on a higher risk of repeated atrial fibrillation in subjects with a lower level of apelin." (PMID 32121175, 2020). "A lower initial apelin serum concentration may indicate a group of patients with a more advanced stage of hemodynamic disorders caused by atrial fibrillation." (PMID 29721104, 2018). "It is investigated whether apelin, among other biochemical markers, has its potential in predicting the risk of atrial fibrillation recurrence after electric cardioversion." (PMID 29721104, 2018). "Taken together, the apelin system protects against the development of atrial fibrillation by influencing electrical conduction and there is further evidence of its potential antithrombotic actions." (PMID 37956047, 2023). "Apelin, a known cardioprotective adipokine, has been shown in an animal study to reduce angiotensin II-induced atrial fibrosis and atrial fibrillation." (PMID 37623336, 2023). "This theory also corresponds with experimental findings showing that apelin increases atrial conduction velocity, refractoriness, shortens action potential, affects multiple ionic currents and prevents the inducibility of atrial fibrillation." (PMID 34712712, 2021). "Our results showed that low level of apelin has good sensitivity for atrial fibrillation even in the setting of multiple cardiovascular comorbidities that increase the risk of ischemic stroke." (PMID 34712712, 2021). "Plasma levels of apelin are substantially lower in patients with atrial fibrillation than in healthy subjects." (PMID 32121175, 2020). "Previous studies have shown an association between elevated atrial NADPH-dependent oxidative stress and decreased plasma apelin in patients with atrial fibrillation (AF), though the basis for this relationship is unclear." (PMID 32879139, 2020). "In conclusion, our data confirm the contribution of apelin to the atrial fibrillation pathophysiology." (PMID 29721104, 2018). "It has been documented that apelin plasma level is reduced in patients with isolated atrial fibrillation and other supraventricular arrhythmias." (PMID 29721104, 2018). "Compared with control subjects with sinus rhythm, patients with atrial fibrillation had significantly lower plasma apelin levels." (PMID 29302260, 2017). "It was demonstrated that apelin can reduce heart rate and inducibility of atrial fibrillation." (PMID 37057103, 2023). "In patients with atrial fibrillation and thrombosis, expression of apelin and the apelin receptor was reduced and expression of AT1 receptors and PAI-1 was increased in the left atrial appendage compared to those in sinus rhythm or atrial fibrillation without thrombosis." (PMID 37956047, 2023). "Increasing circulating apelin in patients with atrial fibrillation could be a future therapeutic strategy, and apelin may be useful biomarker for atrial fibrillation." (PMID 37956047, 2023). "Among other substances, the role of apelin in atrial fibrillation became an object of interest." (PMID 29721104, 2018). "Recently, in individual reports, it was shown the mean apelin level is significantly reduced in patients with isolated atrial fibrillation and normal heart in echocardiography, when compared to the healthy control, and it is also decreased in patients with other supraventricular tachyarrhythmias." (PMID 29721104, 2018).